TSC2 (TSC complex subunit 2)
Diseases named in the same sentence as TSC2 in open-access papers (continued):
Sharing a sentence is not in itself a finding about the gene and the disease.
leiomyoma (10 papers, 2007 to 2020). A well-circumscribed benign smooth muscle neoplasm characterized by the presence of spindle cells with cigar-shaped nuclei, interlacing fascicles, and a whorled pattern. "The role of the IGF-I pathway in leiomyoma development has been well studied in a rodent model for this disease, the Eker rats in which leiomyomas are hormonally responsive tumors derived from a mutation in the Tsc-2 tumor suppressor gene." (PMID 28930160, 2017). "By analyzing Tsc2-null mouse embryonic fibroblasts (MEFs) and rat uterine leiomyoma-derived Tsc2-null ELT3 cells, we detected evidence for the involvement of cyclooxygenase 2 (COX2) as a downstream target of mTORC1 in the development of TSC tumors." (PMID 27078846, 2016). "Mouse model studies also showed increased expression of AdPLA2 in xenograft tumors, estrogen-induced lung metastatic lesions of Tsc2 null leiomyoma-derived cells, and spontaneous renal cystadenomas from Tsc2+/− mice." (PMID 25347447, 2014). "TSC2-null ELT3 smooth muscle cells derived from Eker rat uterine leiomyomas develop tumors in nude mice, and Tsc2−/− rat embryonic fibroblasts show capacity for anchorage-independent growth, one of the hallmarks of the invasive cell phenotype." (PMID 25360538, 2014). "The upregulation of mTOR signaling is also observed in human smooth muscle tumors of the uterus known as leiomyomas and similar tumors were developed in Eker rat with defective TSC2 signaling confirming that the mTORC1 pathway plays an important role in the pathogenesis of these tumors." (PMID 22916036, 2012).
Obesity (10 papers, 2014 to 2025). Accumulation of substantial excess body fat. "In vivo, diet-induced obesity, diabetes, and fatty liver couple to Akt activation and are also unaltered by TSC2 S1364 mutations." (PMID 35288456, 2022). "This study identified upregulated neural mTOR signaling through TSC2 knockout as a key mechanism that predisposes to the HFD-associated onset of normal weight obesity." (PMID 36586433, 2022). "Previous data indicates that TSC2 elimination impairs mitophagy, showing mitochondrial alterations involved in insulin resistance, obesity and other diseases." (PMID 38822085, 2024). "Akt-mTORC1 signaling potently contributes to diet-induced obesity with diabetes and liver steatosis, and we find these effects are unaltered in homozygous TSC2 knock-in mice expressing S1364A or S1364E." (PMID 35288456, 2022). "Oenocyte-specific knockdown of tsc2 along with pvrDN over-expression (oenots>pvrDN,tsc2-i) significantly rescues the obesity phenotype observed flies with oenocyte-specific over-expression of pvrDN (p<0.001)." (PMID 33107824, 2020). "tsc2 knockdown strongly suppressed the obesity phenotype induced by oenocyte-specific expression of pvrDN." (PMID 33107824, 2020). "Adult female TSC2-KOPlacenta mice display hypoinsulinemia in HFD-induced obesity." (PMID 34032632, 2021). "Recent studies indicate that Burkholderia species carry out the microbial conversion of tryptophan into 5-HIAA via a non-traditional pathway, and then activates the AhR/TSC2/mTORC1 axis to improve glucose intolerance and obesity." (PMID 41273480, 2025). "However, 5-HIAA derived from gut microbiota can improve glucose intolerance and obesity in HFD-fed mice, while preserving hepatic insulin sensitivity via directly activating AHR, which stimulates TSC2 transcription and thus inhibits mTORC1 signaling." (PMID 39426289, 2024). "Moreover, we have also found that mTORC1 is activated in podocytes of nondiabetic obese patients with CKD, so an evaluation of the involvement of the Tsc2 gene in nondiabetic obese patients with CKD might provide valuable clues for understanding the pathogenesis of obesity-related renal diseases." (PMID 32191726, 2020).
prostate carcinoma (10 papers, 2011 to 2025). A carcinoma that arises from epithelial cells of the prostate gland. "Interestingly an inactivating splice variant of TSC2 unique to African American patients with prostate cancer has also recently been linked to aggressive prostate cancer and therapeutic resistance." (PMID 32630372, 2020). "In prostate cancer, the frequency of TSC1 and TBC1D7 mutation or deep deletion is low (≤0.8% incidence), whereas TSC2 mutation and deep deletion are more frequent (1–1.8% and up to 4.2% of cases respectively)." (PMID 32630372, 2020). "However, by using logistic regression strategy, we found and validated that several VUS-containing genes (COL1A1, CSF3R, ERBB2, ITGB8, TSC1 and TSC2) in the PI3K-Akt signaling pathway can improve the predicting of metastasis in prostate cancer patients in Hong Kong and Shanghai cohorts." (PMID 36095024, 2022). "Specific splice variants of PIK3CD, TSC2, and RASGRP2 are associated with a more aggressive oncogenic phenotype in AA prostate cancer cells, which has been hypothesized as an underlying mechanism for prostate cancer health disparities between AA and EA men." (PMID 30463359, 2018). "Down-regulation of TSC1 and TSC2 as well as up-regulation of B-Raf caused by elevation of AKT3 may therefore contribute to the increase of cellular proliferation and provide growth advantage for prostate cancer cells." (PMID 26318033, 2015). "There is a study showing that AKT3 can promote prostate cancer cell proliferation by regulating Akt, B-Raf, and TSC1/TSC2." (PMID 36593867, 2022). "Remarkably, up to 3%, 4%, and 7% of patients with prostate cancer also display TBC1D7, TSC1, and TSC2 high-level amplification respectively, yet the functional consequence is currently unclear." (PMID 32630372, 2020). "Our experimental results showed that AICAR enhances the expression of TSC1 and TSC2, whereas it reduces the expression of mTOR and MYC as well as decreases the phosphorylation of p70S6K in 22Rv1 prostate cancer cells." (PMID 30987073, 2019). "We discovered that the elevation of AKT3 promoted the proliferation of different prostate cancer cell lines via induction of AKT phosphorylation and B-Raf as well as the reduction of TSC1 and TSC2." (PMID 26318033, 2015). "In conclusion, our observations suggested that elevation of AKT3 promotes the proliferation of prostate cancers cells through regulation of Akt, B-Raf, & TSC1/TSC2." (PMID 26318033, 2015). "As cDNA overexpression of AKT3 and siRNA knockdown of AKT3 showed opposite effects on phospho-AKT S473, phospho-AKT T308, B-Raf, TSC1 and TSC2, these proteins may play essential roles in the proliferation regulation of AKT3 in prostate cancer cells." (PMID 26318033, 2015). "As overexpression of AKT3 decreased protein level of TSC1 and TSC2, we hypothesized that knockdown of TSC1 or TSC2 will enhance proliferation of prostate cancer cells." (PMID 26318033, 2015).
brain tumor (9 papers, 2015 to 2025). "Volcano plots of the differentially expressed genes illustrate the dysregulation of NF-κB-linked genes in TSC patient-derived brain tumours and in TSC2(−) AML cells compared with their respective wild-type controls." (PMID 41013689, 2025). "Volcano plots of differentially expressed genes illustrate dysregulation of NF-κB-linked genes in TSC patient-derived brain tumours, and TSC2(−) AML cells when compared with their respective wild-type controls." (PMID 39070657, 2024). "Genotypes ranging from point mutations to large deletions in the TSC2 gene have been clinically characterized with a wide range of phenotypes from skin tumors to large brain tumors." (PMID 35947627, 2022). "Because of the deficiency of Tsc2, the activity of the Tsc1/Tsc2 complex is decreased, leading to the overactivation of the mTOR pathway, which is the primary cause of TSC-related symptoms, including tumours of the brain, skin, heart, lungs, and kidney." (PMID 34576223, 2021). "The third hospital is a reference for brain tumor treatment and follows up severe patients with genetic tumor syndromes referred to by neurologists, which may additionally justify a higher number of patients with TSC2 alterations." (PMID 39596632, 2024).
depression (9 papers, 2011 to 2025). "ADHD, anxiety disorder, and depressive disorder were associated with TSC1 rather than TSC2 (ADHD TSC1 = 17.6%; TSC2 = 16%, p = 0.6881; anxiety disorder TSC1 = 10.1%; TSC2 = 8.6%; p = 0.7809; depressive disorders TSC1 = 10%; TSC2 = 5.2%; p = 0.0509)." (PMID 39852149, 2025). "Protein products of MTOR and TSC2 are implicated via their connections with AKT1 in regulation of synaptic plasticity and memory; these are impaired in depression, possibly as a result of a reduction of hippocampal volumes." (PMID 33193575, 2020). "Supporting this notion is the fact that a genetic cross between Fmr1 KO and Tsc2+/- mice normalized long-term depression as well as performance in a contextual fear conditioning task." (PMID 29375310, 2017). "For example, the ubiquitous protein, UBC, was abnormally expressed in schizophrenia samples and interacted with the maker genes of schizophrenia (i.e. TSC2, SCNN1A and USP2), bipolar disorder (i.e. MUSK), and major depression (i.e. MUSK and FLT3)." (PMID 22373040, 2011). "ASD was observed at a significantly higher frequency in participants with TSC2 than those with TSC1 mutations, while ADHD, anxiety disorder, and depressive disorder were more associated with TSC1 rather than TSC2, indicating a more severe neuropsychiatric phenotype being associated with TSC2." (PMID 39852149, 2025).
glioma (9 papers, 2019 to 2025). A benign or malignant brain and spinal cord tumor that arises from glial cells (astrocytes, oligodendrocytes, ependymal cells). "By delving into the CGGA database to analyse the correlations between ApoE and genes associated with glioma growth and resistance, we found that ApoE has a positive correlation with TSC2, a well‐recognised tumour suppressor gene." (PMID 40662483, 2025). "26,27 Other notable transcriptional differences in EGFRvIII-containing samples include increased HDAC6 expression, reported to promote glioma proliferation; increased expression of the stem cell marker SOX9; and increased expression of tumor suppressor TSC2." (PMID 38665799, 2024). "JHU-083 reduced glioma cell growth in vitro, modulated cell metabolism, and disrupted mTOR signaling and downregulated Cyclin D1 protein expression, through a mechanism independent of TSC2 modulation and glutaminolysis." (PMID 33681764, 2021).
Insulin resistance (9 papers, 2009 to 2024). Increased resistance towards insulin, that is, diminished effectiveness of insulin in reducing blood glucose levels. "Previous works demonstrated that loss of tumour suppressor tuberous sclerosis complex 2 (TSC2) gene leads to insulin resistance due to reduction in Akt phosphorylation." (PMID 26387534, 2015). "Insulin resistance is associated with hyperinsulinemia; however, we found significant hypoinsulinemia at week 4 of HFD in male TSC2-KOPlacenta compared with littermate controls." (PMID 34032632, 2021). "Moreover, the homeostatic model assessment of insulin resistance (HOMA-IR) at 6 weeks of HFD was comparable between TSC2-KOPlacenta and littermate controls." (PMID 34032632, 2021). "Deficiency of PKBα/β caused insulin resistance in mouse heart, and the abundance of their substrates including AS160, RalGAPα1, RalGAPα2, and TSC2 in the PAS immunoprecipitates was substantially lower for PKBα/β-deficient mouse heart relative to wild-type mouse heart upon insulin stimulation." (PMID 32367034, 2020). "We find that, despite severe insulin resistance and the absence of Akt signaling, TSC2-deficient mouse embryo fibroblasts and 3T3-L1 pre-adipocytes display enhanced adipocyte differentiation that is dependent on the elevated mTORC1 activity in these cells." (PMID 19593385, 2009). "These investigations suggest that reduced expression of KLF4 triggered by a high-fat diet in our mouse model (IR+/-IRS1+/-ApoE-/-) may mediate down-regulation of IRS2 and TSC2 expression thereby impairing insulin signaling in adipocytes and promoting insulin resistance." (PMID 30240435, 2018). "When applying BAKE to an experimental animal model of insulin resistance progression, we discovered a novel regulatory transcription factor KLF4 to interact with IRS2 and TSC2, two key intermediates in the insulin signaling pathway." (PMID 30240435, 2018). "Model behavior has been tested on a variety of conditions: muscle cells with Pten KO or with induced insulin resistance, knockdown and overexpression of PRAS, TSC2-null cells, cells treated with rapamycin and anticancer drugs such as AZD8055 and UCN-01." (PMID 27149630, 2016). "To investigate whether galangin can get insulin resistance better, we examined the phosphorylation state of ten proteins on the Akt/mTOR signal pathway, including IR, IRS1, PTEN, Akt, GSK3α, GSK3β, TSC2, mTOR, p70S6K, and RPS6." (PMID 30420897, 2018).
melanoma (9 papers, 2015 to 2026). A malignant, usually aggressive tumor composed of atypical, neoplastic melanocytes. "Melanoma cells from mice on a HSD upregulated the metabolic inhibitor Tuberous sclerosis complex 2 (TSC2), causing metabolic shutdown despite nutrient availability." (PMID 41422056, 2025). "For example, in melanoma models, iNOS-generated NO can reversibly S-nitrosylate the TSC2 protein, disrupting TSC2/TSC1 dimerization, leading to mTOR activation and increased melanoma cell proliferation." (PMID 39737957, 2024). "The presence of melanoma markers in lung is atypical and is used as a diagnostic indicator of LAM; it is likely that these cells carry the TSC2 mutation." (PMID 25978616, 2015).
multiple myeloma (9 papers, 2018 to 2025). "We have previously shown that multiple myeloma cells, deficient for TSC2, gain sensitivity to proteasome inhibitors and hypoxia." (PMID 39013537, 2024). "The results reported herein establish a basis forthe development of new inhibitors blocking the binding of TSC2 andRheb, aiming to reinstate mTORC1 activation and facilitate improvedefficacy of PIs against multiple myeloma." (PMID 39947931, 2025). "It is known that PIM2 modulates TSC2 phosphorylation and thus maintains multiple myeloma cell growth." (PMID 33931981, 2021). "Previously, PIM was also reported to inactivate TSC2 by phosphorylating S1798 of this negative regulator for mTORC1 in multiple myeloma cells." (PMID 31756944, 2019). "For example, PIM2 targets the TSC2 protein and enhances the mTOR‐C1 pathway to maintain cell growth in multiple myeloma, representing an important target in the treatment of tumor progression and bone loss in myeloma." (PMID 29570932, 2018). "PIM2 phosphorylates TSC2 on Ser1798 and relieves the suppression of TSC2 on mTOR-C1 which could be a promising therapeutic target for multiple myeloma." (PMID 29985480, 2018). "Metformin has been reported to regulate the G0/G1 cell-cycle arrest in myeloma cell lines in vitro by inducing autophagy via activated AMPK and repressing both the mTORC1 and mTORC2 signaling pathways via p-4EBP1, p-AKT, and TSC2." (PMID 33375360, 2020).
glioblastoma (8 papers, 2014 to 2025). The most malignant astrocytic tumor (WHO grade IV). "Some examples of successful treatments of glioblastoma patients with mTOR inhibitors have been reported, such as in the case of a child having a TSC2-mutant glioblastoma who achieved complete remission under everolimus therapy." (PMID 35743016, 2022). "Deletion of TSC2 in the glioblastoma GL261 cells enhanced their sensitivity to IXZ, while deletion of ATG7 did not, similar to MM." (PMID 36400754, 2022). "Although a counterintuitive finding, an increased level of p-S6K1 has been observed previously in TSC2 overexpressing mouse embryonic fibroblast and glioblastoma cells." (PMID 24748662, 2014). "While the TSC2 mutation in conjunction with high mTOR expression may suggest treatment with everolimus, clinical evidence of activity in glioblastoma has not been supportive." (PMID 34943910, 2021).
Granuloma (8 papers, 2018 to 2025). A compact, organized collection of mature mononuclear phagocytes, which may be but is not necessarily accompanied by accessory features such as necrosis. "It was recently shown that the constitutive activation of mTORC1 in a mouse model deficient for TSC2 promotes granuloma formation through a metabolic reprogramming mediated by CDK4, suggesting a crucial role of the TSC1/TSC2 complex and mTor pathway in granulomatous diseases." (PMID 29510755, 2018). "Conditional myeloid deletion of the Tsc2 gene, which encodes the tuberin protein (an inhibitor of the mTORC1 complex), resulted in mTORC1 activation in macrophages and the spontaneous formation of granulomas in mice, primarily in the lungs, liver, skin, and lymph nodes." (PMID 39996765, 2025). "Here, we show that aberrantly increased monocytopoiesis gives rise to granulomas in a sarcoidosis model, in which Tsc2, a negative regulator of mTORC1, is conditionally deleted in CSF1R-expressing macrophages (Tsc2csf1rΔ mice)." (PMID 38147536, 2024). "Similar to the lung granuloma clusters from the Tsc2-dependent sarcoidosis mouse model, we also found increased Ki-67-positive expression in the patient macrophage clusters." (PMID 38353578, 2024). "It reports the development of granuloma in a mouse model with constitutive activation of mTORC1 in myeloid cells and thus in macrophages (obtained by deletion of tsc2)." (PMID 35740604, 2022). "It has been demonstrated in a mouse model that granuloma can be formed spontaneously when the mTORC1-inhibitor TSC2 is depleted." (PMID 32760396, 2020). "The Tsc2 knockout mice exhibit spontaneous systemic tissue granuloma formation with features resembling those of sarcoidosis patients with active disease progression, including epithelioid-like macrophages, M2 macrophage polarization, and mTORc1 pathway activation." (PMID 32849608, 2020).
kidney cancer (8 papers, 2016 to 2022). Primary or metastatic malignant neoplasm involving the kidney. "The findings suggest that genes associated with kidney cancer, including VHL, MET, FH, FLCN, TSC1, TSC2, and SDH, are involved in metabolic pathways linked to oxygen and iron or nutrient sensing, thus characterizing kidney cancer as a cellular metabolic disease." (PMID 35873461, 2022). "Multiple genes linked with kidney cancer, including the VHL, MET, FLCN, fumarate hydratase, succinate dehydrogenase, TSC1, TSC2, and TFE3, were identified by genomic studies and have significantly altered the ways in which patients with kidney cancer are managed." (PMID 29254180, 2017). "Recently, several characteristic kidney cancer-related genes, including VHL, MET, FLCN, TSC1, TSC2, FH, and SDH, have been reported to affect the metabolic stress response." (PMID 33686951, 2021). "Previous studies have shown that seven known kidney cancer genes, VHL, MET, FLCN, TSC1, TSC2, FH, and SDH, are involved in pathways that respond to metabolic stress or nutrient stimulation, suggesting that kidney cancer is a disease of dysregulated cellular metabolism." (PMID 31649873, 2019).
pancreatic cancer (8 papers, 2015 to 2023). "Here, we report a case of stage IV pancreatic cancer in a patient with TSC2 and SMAD4 mutations treated with immunotherapy when the disease progressed after multi-line chemotherapy." (PMID 34880877, 2021). "These deceased participants had actionable findings in PALB2 and TSC2 indicating breast and pancreatic cancer risk and tuberous sclerosis type II, respectively." (PMID 32377377, 2020). "This outcome reveals that this combination can be effective in treating metastatic pancreatic cancer, especially in pancreatic cancer patients with SMAD4 and TSC2 mutations." (PMID 34880877, 2021). "However, only miR-103 was directly involved in the regulation of pancreatic cancer-associated processes: E-cadherin signalling events (CDH1), TGF beta signalling pathway (TGFBR2, APC, CDH1, CREBBP, EP300, SMAD3, TSC2), and altered TFG-beta SMAD dependent signalling (TGFBR2, SMAD3, and FBXW7)." (PMID 29285254, 2017).